CD81 (CD81 molecule)
Diseases named in the same sentence as CD81 in open-access papers (continued):
Sharing a sentence is not in itself a finding about the gene and the disease.
breast carcinoma (continued). "In breast cancer, suppression of CD81 using shRNA resulted in the decrease of cell migration in vitro and led to the reduction of primary tumor growth, extravasation and lung metastasis in vivo." (PMID 33919192, 2021). "CD81+ CAF-derived exosomes promote breast cancer cell protrusions and motility, and tumor metastasis in vivo; breast cancer cell produced Wnt11 interacts with exosomes received from CAFs to activate PCP signaling." (PMID 32957712, 2020). "CD81 positive exosomes derived from CAFs activated Wnt-planar signal pathway and promoted the migration and lung metastasis of breast cancer cells." (PMID 31064356, 2019). "The principle behind the biosensor involves the monitoring of changes in electrochemical signals due to bio recognition reaction between anti-CD81 antibody and CD-81 present on the lipid membrane of breast-cancer EVs." (PMID 29925885, 2018). "In mouse models of breast cancer, cancer-associated fibroblast-derived exosomes are enriched in tetraspanins CD63, CD81, and CD82 but only CD81 is responsible of Wnt 11 cargo to EVs." (PMID 25278937, 2014). "After preliminary experiments, in which silencing CD9 or CD81 alone in MDA-MB-231 breast cancer cells produced only modest phenotypic changes, we established cells with stable silencing of both tetraspanins (CD9/81si cells)." (PMID 23613949, 2013). "Moreover, since the five proteins CD9, CD24, CD63, CD81, and MMP9 are universal and present in exosomes secreted by both primary endotheliocytes and breast carcinoma cells, they cannot be part of the diagnostic panels being developed." (PMID 40310419, 2025). "Additionally, CD81 expression in melanoma has been shown to promote tumor growth and metastasis in humans, and CD81 knockout in osteosarcoma and breast cancer cells attenuates tumor progression and dissemination." (PMID 39051897, 2024). "Using DISVT and our machine learning-assisted image analysis platform, we determined the fractions of EpCAM-positive EVs and CD24-positive EVs over captured plasma EVs with CD81 marker in the blood plasma of pilot HER2-positive breast cancer patients and compared to those from healthy donors." (PMID 39513819, 2024). "Interestingly, decreased CD81 expression has been associated with increased metastatic capacity in liver cancer and bladder cancers, while the knockdown of CD81 has been shown to decrease cell motility and metastasis in melanoma and breast cancer." (PMID 38136327, 2023). "Interestingly, in the field of cancer, CD81 was expressed in many malignancies, including breast cancer, lung cancer, prostate cancer, melanoma, lymphoma, and brain tumor, and its overexpression was correlated with a poor prognosis." (PMID 36979448, 2023). "We developed and validated a platform based on nanowell arrays for directly profiling EV secretion from single cells and used these to establish cells derived from a clinically relevant mouse breast cancer model that have significant differences in the rate of secretion of CD81+CD63+EVs." (PMID 34503207, 2021). "For example, CD81+ exosomes are shed by CAFs and can be internalized by breast cancer cells, altering Wnt pathway molecules, which may contribute to an increase in cell protrusions and motility, favoring the metastasis cascade." (PMID 34898576, 2021). "For instance, while the expression of the TSPAN CD81, also known as TSPAN28, in breast cancer, multiple myeloma, and acute myeloid leukemia is considered a marker for worse prognosis, in patients with gallbladder carcinoma, its expression indicates a favorable outcome." (PMID 34065085, 2021). "Moreover, CD81 contributes to the migration of dendritic cells and the motility of breast cancer cells." (PMID 34824296, 2021). "Thus, CD81 and Pax5-induced CD81 appeared to function as a positive regulator of cell motility, which is in agreement with previous reports using dendritic, breast cancer, and B cells." (PMID 34824296, 2021).
breast carcinoma (continued). "Furthermore, CD81 knockdown results in decreased proliferation and migration in mammary carcinoma cell lines in vitro." (PMID 31565104, 2019). "Wnt11 and CD81 are localized on EVs, and the internalization of CD81 molecules on the EVs in breast cancer cell may support the endocytic trafficking of autocrine Wnt ligand to activate the Wnt-PCP pathway." (PMID 27582126, 2017). "While all of these studies pointed towards possible integrin-dependent functions for the CD9/CD81 complex in breast carcinoma cells, the specific integrins involved in each study were not defined, and, in particular, the specific contribution of α3β1 integrin was not assessed." (PMID 23613949, 2013). "Additionally, CD81 was abundantly expressed in breast cancer tissues compared to normal tissues." (PMID 36979448, 2023). "Furthermore, a subset of CTCs and tumor-initiating cells may exhibit dynamic changes in epithelial–mesenchymal transition phenotype, which can upregulate CD81 expression in mesenchymal breast cancer." (PMID 36193887, 2022). "Recent findings that the CD9/CD81 tetraspanin complex regulates α3β1 integrin-dependent tumor cell behavior and that integrin α3β1 promotes breast carcinoma metastases suggests that the anti-metastatic effect observed upon CD9 knockdown could depend on the CD9 regulation of α3β1-integrin." (PMID 25762645, 2015). "By functionalizing AuNSt with either polyarginine (AuNSt@PA) or anti‐CD81 antibody (AuNSt@AB), we achieved simultaneous cell‐type identification and selective tracking of small EV‐mediated transfer from MCF‐7 breast cancer cells to HDF cells." (PMID 41254992, 2026). "Conversely, in plasma-enriched sEVs from stage IV breast cancer patients, HPA binding was most abundant on CD81-captured sEVs, followed by CD9, with the least binding on CD63-captured sEVs." (PMID 40411659, 2025). "HPA labelling in conjunction with ExoView analysis confirmed the co-localisation of CD63, CD81, and CD9 in both MCF-7 cell-derived sEVs and plasma-enriched sEVs derived from stage IV breast cancer patients." (PMID 40411659, 2025). "Breast cancer plasma EVs displayed a unique proteome profile, with typical EV markers, such as CD9, CD81, CD63, and HSP70; Rab proteins; and clathrin." (PMID 37629204, 2023). "Mouse models of breast cancer were coinjected with breast cancer cells (BCCS) and fibroblasts, leading to increased metastasis dependent on EV cargo CD81 in fibroblasts and Wnt-planar cell polarity (PCP) signaling in BCCs." (PMID 35454972, 2022). "TβRII is rather abundant and specifically enriched in EVs from metastatic breast cancer cells as its expression intensity even exceeds EV markers such as CD9 and CD81." (PMID 35915084, 2022). "In summary, the surface protein profile of EVs from breast cancer patients suggested that EVs with the typical EV markers CD9, CD63 and CD81 were of cancer cell origin, as well as released by antigen-presenting cells and platelets." (PMID 35012489, 2022). "The expression of characteristic markers for exosomes and EVs varied, but all EV lysates from breast cancer lines were positive for CD9 and CD81, whilst the presence of CD63 was more variable." (PMID 35318648, 2022). "Both the breast cancer and melanoma studies have focused on the impact of CD81+CD63+EVs in inhibiting lung metastasis and it remains to be seen if this impact of CD81+CD63+EVs is restricted to the lung or if it also impacts metastasis to the other organs." (PMID 34503207, 2021). "By identifying and implementing signatures of CD81+CD63+EVs within the TCGA, we were able to circumvent the differences in the immune microenvironment in mouse tumors such as 4T1 and human breast cancers." (PMID 34503207, 2021). "Our data reveal that the CD9/CD81 complex and CD151 have overlapping but distinct functions in regulating α3β1-dependent behaviors in the MDA-MB-231 breast cancer model." (PMID 23613949, 2013).
breast carcinoma (continued). "To begin to clarify which aspects of α3β1 function require which tetraspanins, we created breast carcinoma cells depleted of both CD9 and CD81 by RNA interference." (PMID 23613949, 2013). "If PKCα does promote breast cancer metastasis through α3β1 integrin, our new data strongly suggest that the CD9/CD81 complex plays a key role." (PMID 23613949, 2013). "We characterizethe EV secretion of two breast cancer cell lines: triple-negativeMDA-MB-231 cells and HER2-positive SkBr3 cells secrete EVs that carrydistinguishable levels of tetraspanins (CD9, CD63, and CD81) and HSPs(−90 and −70)." (PMID 41489814, 2026). "In breast cancer, Luga and colleagues first confirmed that CAF-secreted sEVs with a high CD81 expression can promote breast cancer cell motility and metastasis via Wnt-planar cell polarity (PCP) signaling, and this response was dependent on the exosome component CD81 in CAFs." (PMID 39684264, 2024). "Since CD81 was reported to promote cancer cell migration, an initial step in metastasis, the Boyden chamber assay, was next performed to assess the effect of CD81-BP candidates on the migration of MDA-MB-231 human breast cancer cells." (PMID 36979448, 2023). "Wnt11 aids cell migration and metastasis in breast cancer cells, and the sorting of the Wnt11 cargo to EVs is supported by CD81, but not other tetraspanins." (PMID 33669943, 2021). "Based on the mice data, we hypothesized that the inability to form tumors can be associated with immune response, and thus we sought to directly understand the impact of CD81+CD63+EVs and the link to the immune system within human patients with breast cancer." (PMID 34503207, 2021). "Collectively, studies with these non-metastatic breast cancer cells demonstrated that despite enhanced tumor-forming potential in vitro, cell lines secreting CD81+CD63+EVs were rejected in vivo, presumably due to the host immune system." (PMID 34503207, 2021). "In addition, this nanosensing technique is able to quantify exosomes with different surface biomarker expressions and has revealed that exosomes secreted from MCF-7 breast cancer cells have a higher CD24 expression compared to CD63 and CD81." (PMID 36133621, 2019). "After optimization of the exosome isolation from MDA-231 breast cancer cells in 2D cultures we verified the successful exosome harvesting through TEM and immunoblot protein analysis of well-established exosome markers CD63 and CD81." (PMID 29137633, 2017). "In addition, anti-human CD81 antibody (5A6) could effectively inhibit in vitro migration and invasion, as well as in vivo metastasis of MDA-MB-231 human breast cancer cells." (PMID 36979448, 2023). "Indeed, Luga and colleagues demonstrated that EVs released from cancer-associated fibroblasts (CAFs) promote the increased motility and metastatic capability of breast cancer cells, which is dependent on the interaction of breast cancer cell-produced Wnt11 and CAF-derived CD81." (PMID 37760975, 2023). "Indeed, CD81 functions in breast cancers are not clear, its expression being correlated to either bad or good prognosis." (PMID 34207462, 2021). "Moreover, deleting CD81 in endothelial-producing exosome cells but not tetraspanins CD63 or CD82 reduced breast cancer motility and metastasis." (PMID 29946318, 2018). "Also unexpectedly, the CD9/CD81 complex, but not CD151, was required to promote α3β1 association with PKCα in breast carcinoma cells, and a PKC inhibitor mimicked aspects of the CD9/CD81-silenced cell motility defect." (PMID 23613949, 2013). "Overall, these data indicate that the ability of the CD9/CD81 complex to promote α3β1 integrin-dependent motility is not restricted to the MDA-MB-231 breast cancer model, although, unlike MDA-MB-231 cells, A431 cells also exhibit an ongoing requirement for CD151 for rapid migration on LM-332." (PMID 23613949, 2013). "Western blot analysis showed that the Luc2 mouse mammary carcinoma cells expressed CD9 and CD81 but not CD63." (PMID 39273689, 2024).
breast carcinoma (continued). "To identify signatures of CD81+CD63+EVs, we applied unsupervised hierarchal clustering to stratify non-metastatic breast cancer patients into two groups with 182 and 268 patients each." (PMID 34503207, 2021). "To assess if other human mammary epithelial cells release exosomes, we quantified the abundance of CD81 and CD63, an endosomal marker protein, in P70 preparations of breast cancer cell lines MDA-MB-231, BT-20, and the nontumorigenic mammary epithelial cell line MCF 10A." (PMID 20976003, 2010). "Moreover, recent studies in breast cancer cells have shown the release of hypothetical “non-classical” exosomes generated by amphisomes (produced by fusion of multivesicular bodies -MVB- and autophagosomes)), lacking classical exosome markers (CD63, CD81, and CD9)." (PMID 38268920, 2023).
melanoma (47 papers, 2011 to 2025). A malignant, usually aggressive tumor composed of atypical, neoplastic melanocytes. "CD81 expression has been strongly associated with cancerous pathologies, and has been shown to promote tumor growth and metastasis in human melanoma, while its knockdown in osteosarcoma models has reduced tumor progression." (PMID 36504839, 2022). "We also show that the CD81+CD63+EV secretion signatures were associated with improved overall survival in melanoma (SKCM) patients." (PMID 34503207, 2021). "We transduced them into human melanoma (A375) cells and monitored CD81 loss." (PMID 31784531, 2019). "Similarly, CD9/CD81 were shown to regulate TGF-β1 signaling in melanoma by providing critical support for TGFβR2- TGFβR1 association, which in turns favors EMT-like changes, invasion, and metastases." (PMID 29946318, 2018). "Of note, to better explore LEVs markers, we demonstrate tetraspanin labelling (CD9, CD63 and CD81) in our LEVs isolates from pooled plasma samples from nevi and melanoma patients." (PMID 41268555, 2025). "The levels of expression of these two compounds are strictly correlated; in fact, a recent study on human SK-MEL-28 melanoma cells reported that SNCA-KO leads to a significant decrease in CD81 levels." (PMID 41460324, 2025). "This idea is borne out by our previously published work showing that individuals with melanomas with expression of both α-syn of CD81 have significantly diminished survival." (PMID 40521809, 2025). "Of the three tetraspanins (CD9, CD63, and CD81) we have studied in the context of melanoma, only CD81 affects patient survival." (PMID 40521809, 2025). "We recently reported a significant reduction in the level of the CD81 protein in SNCA-KO melanoma cells relative to control cells and found that some of the lower expression is due to a 40% reduction of CD81 mRNA in the KO cells." (PMID 40521809, 2025). "focused on the lipid profiling of CD81 exosomes, a subpopulation of small EVs (sEVs), from melanoma patients and healthy donors (HDs)." (PMID 40111100, 2025). "In summary, they suggested that CD81+CD63+EVs contribute to restricting metastasis development in breast and melanoma in lung tissue and that tumors with low levels of CD81+CD63+EVs have a high tendency to develop lung metastasis." (PMID 39091989, 2024). "CD81 also contributed to motility, invasion, and metastasis of melanoma, by inducing the expression of membrane type 1 matrix metalloproteinase in the Akt-dependent Sp1 activation signaling pathway." (PMID 36979448, 2023). "For example, using immunocapture with anti-CD81 coated beads, not only proteins but also fatty acids have been profiled in plasma-circulating CD81-EVs showing an increase in fatty acid content in melanoma late stages compared to healthy donors." (PMID 36704194, 2022). "Co-expression of CD9/CD81 was shown to regulate TGF-β1 signaling in melanoma by providing critical support for the TGFβR2-TGFβR1 association, which in turns favors epithelial to mesenchymal transition-like changes, invasion, and metastases." (PMID 33669943, 2021). "In these particular melanoma vesicles, the expression levels of tetraspanins CD81 and CD9 as well as of MHC-I are limited, so that their changes in MFI values are small throughout the range of sample dilutions." (PMID 28900146, 2017). "Flow cytometry revealed a clear CD81+/Rh+ population (pink gate) demonstrating labeling of melanoma exosomes by Rh-HDL NPs." (PMID 26964503, 2016). "In proof-of-concept studies to demonstrate potential diagnostic utility of SR-B1 expression and HDL NPs, we measured CD81 and SR-B1 in exosomes isolated from the serum of patients diagnosed with melanoma." (PMID 26964503, 2016). "Recently a study on the tetraspanin-interacting protein EWI-2 indirectly implicates two other tetraspanins, CD9 and CD81, in regulating TGFβ signaling in melanoma growth and metastasis." (PMID 25978409, 2015).